SOCS1 (suppressor of cytokine signaling 1)
Diseases named in the same sentence as SOCS1 in open-access papers (continued):
Sharing a sentence is not in itself a finding about the gene and the disease.
uveitis (11 papers, 2016 to 2025). An inflammatory process affecting a part of or the entire uvea. "Using rodent models of uveitis, we have demonstrated that the topical administration of SOCS1-KIR to the eye suppresses both TH1- and TH17- associated cytokines, while promoting the production of IL-1049." (PMID 35505065, 2022). "The SOCS1-Mimetic ameliorated uveitis by suppressing the expansion of pathogenic Th17 cells and trafficking of inflammatory cells into the neuroretina during EAU." (PMID 33995347, 2021). "Analysis of eyes of rats treated with the SOCS1-KIR or control scrambled peptide 12 days after adoptive transfer of pathogenic R16 T cells by histology shows the development of pan uveitis in the rats treated with the scrambled peptide." (PMID 27703302, 2016). "We have previously shown that the topical administration of a peptide mimic of the SOCS1 kinase inhibitory region potently inhibited uveitis in both murine and rat models of induced disease, while also modulating the immune responses guiding those pathologies." (PMID 39867889, 2024). "Significantly, we and others have demonstrated that peptide mimics of the KIR region of SOCS1 can inhibit immune activation and disease progression in in vitro and murine models of disease, including induced models of uveitis." (PMID 39867889, 2024). "Topical administration of SOCS1-KIR peptide was shown to successfully prevent uveitis and ocular damage." (PMID 38022642, 2023). "Several studies have indicated Socs1 as an inflammatory suppressor gene in ocular disorders, including diabetic retinopathy and uveitis 60,61." (PMID 37063422, 2023). "Significantly, we previously showed that topical administration of a SOCS1 peptide mimic (SOCS1-KIR) mitigated induced rodent uveitis." (PMID 35505065, 2022). "(iii) Topical SOCS1-Mimetic therapy: The SOCS1-Mimetic inhibits Jak kinases and is an effective non-invasive treatment for uveitis in mice." (PMID 33995347, 2021). "Photopic and scotopic electroretinograms confirmed the neuroprotective effects of the SOCS1-KIR in uveitis." (PMID 33995347, 2021). "The use of the SOCS1-KIR mimetic peptide to suppress acute as well as relapsing uveitis in this study thus represents an important addition to the armamentarium of remedies for several of the potentially blinding chronic uveitides." (PMID 27703302, 2016). "Of clinical importance, topical administration of SOCS1-KIR induced sustained therapeutic suppression of uveitis 50 days after induction of EAU and this method of drug administration did not cause any apparent discomfort to the mice." (PMID 27703302, 2016). "Taken together, these results suggest that SOCS1-KIR mitigated uveitis, in part, by suppressing the level of inflammatory cells in the retina during EAU." (PMID 27703302, 2016). "The identification of fatal consequences stemming from the lack of SOCS1 across a spectrum of autoimmune, autoinflammatory, and malignant diseases has prompted the exploration of SOCS1 mimetic peptides in various animal experiments especially in the condition of recurrent uveitis." (PMID 38711523, 2024). "Notably, our previous induced uveitis rodent studies demonstrated SOCS1-KIR mediated decreases in the chemokines CCL2, CCL20 and CXCL9, in addition to the chemokine receptors CCR2, CCR4, CCR6 and CXCR35,25." (PMID 35505065, 2022). "In addition, we have shown that the topical application of SOCS1-KIR peptide in a simple eye drop form mitigated experimentally induced uveitis in mice and rats." (PMID 35505065, 2022). "Furthermore, it has been shown that topical administration of a SOCS1 peptidomimetic suppresses uveitis and confers protection from ocular pathology during experimental autoimmune uveitis." (PMID 31344857, 2019). "Taken together, these results suggest that SOCS1 mimetic peptide may be effective for treating both acute and chronic uveitis." (PMID 27703302, 2016).
uveitis (continued). "Deficiency in SOCS1 can lead to JAK2 hyperactivation, exacerbating inflammatory responses, whereas enhancing SOCS1 function could mitigate disease progression, highlighting its therapeutic potential in uveitis." (PMID 40755762, 2025). "As induced rodent models of uveitis have shown that either Th1 or Th17 T lymphocytes can promote experimental uveitis, the ability of SOCS1-KIR to regulate both STAT1 and STAT3 signaling may be particularly valuable in inhibiting uveitogenic effector functions." (PMID 35505065, 2022). "Notably we have shown that a peptide mimic of the kinase inhibitory region of suppressor of cytokine signaling-1, administered as an eyedrop, was effective in both the induced anterior model of murine uveitis and the relapsing remitting rat model of pan-uveitis." (PMID 35505065, 2022). "Defective expression of SOCS1 in patients with scleritis, taken together with studies showing that rats with targeted overexpression of SOCS1 in the retina are protected from uveitis, implies that administration of SOCS1 mimetic peptides may be useful in treating uveitis." (PMID 27703302, 2016). "Thus, SOCS1-KIR suppresses uveitis and confers neuroprotective effects and might be exploited as a noninvasive treatment for chronic uveitis." (PMID 27703302, 2016). "SOCS1-KIR administration also led to significantly reduced TNFα and IL-10 secretion in PHA-stimulated equine PBMCs, isolated from both non-uveitis and ERU horses." (PMID 39867889, 2024). "A pilot study recently examined the safety and effectiveness of the SOCS1 mimetic peptide for treating equine recurrent uveitis (ERU), which serves as a model for human recurrent uveitis (RU)." (PMID 38022642, 2023). "We have previously shown that the topical administration of a peptide corresponding to the kinase inhibitory region of murine SOCS1 (SOCS1-KIR), DTHFRTFRSHSDYRRI, was safe and prevented induced uveitis in murine and rat models of disease." (PMID 35505065, 2022). "Topical administration of a formulation consisting of membrane-penetrating 16 amino acid SOCS1 peptide, with a lipophilic palmitoyl-lysine group attached to its NH2-terminus (SOCS1-KIR), was effective in suppressing uveitis in mice EAU." (PMID 33995347, 2021). "We therefore monitored uveitis in the rat eyes until 50 days after induction of EAU and the rats treated with SOCS1-KIR were found to develop significant lower EAU scores compared to rats treated with control peptides." (PMID 27703302, 2016). "However, it is not clear whether SOCS1-KIR ameliorated uveitis by targeting JAK/STAT pathways of pathogenic lymphocytes or via inhibition of macrophages and antigen-presenting cells that also enter the retina during EAU." (PMID 27703302, 2016). "In our investigation of the effects of SOCS1-KIR administration, we did not specifically activate uveitogenic T lymphocytes, known to cause uveitic damage in the eye of uveitis patients; rather, we activated PBMCs non-specifically." (PMID 39867889, 2024). "The safety of SOCS1-KIR peptide in equine eyes was initially assessed in a pilot study using healthy horses without equine recurrent uveitis." (PMID 38022642, 2023). "In the mouse model of uveitis, inhibition of the JAK/STAT signaling pathway by SOCS1-KIR, which binds to JAK2, could suppress and ameliorate experimental autoimmune uveitis (EAU)." (PMID 34966823, 2021). "Given that SOCS1-KIR regulates Janus kinases in a way that is distinct from current Jakinibs and that kinase regulation is distinct from steroidal mechanisms of action, we are hopeful to have increased options for the treatment of intractable uveitis in the future." (PMID 39867889, 2024). "Importantly, the SOCS1-Mimetic is non-toxic, indicating that topical administration of SOCS1-Mimetics can be exploited as a non-invasive treatment for uveitis." (PMID 33995347, 2021).
chronic myeloid leukemia (10 papers, 2016 to 2022). "For instance, SOCS1 has a role in the development of acute/chronic myeloid leukemia, glioblastoma and Barrett’s adenocarcinoma." (PMID 34349769, 2021). "By contrast, SOCS1 expression in chronic myeloid leukemia correlates with an impaired response to IFN-α and reduced relapsed free survival of those patients." (PMID 33287392, 2020). "SOCS1 expression in chronic myeloid leukemia correlates with poor cytogenetic response to IFN-α and short progression-free survival time." (PMID 28228755, 2017). "Therefore in this study, we determined the DNA methylation status at CpG dinucleotides of DAPK1, RASSF1, p16INK4, p14ARF, RIZ1 and SOCS1 in concert with disease progression, imatinib response and overall survival in chronic myelogenous leukaemia." (PMID 35421941, 2022). "Hence, aberrant SOCS1 expression might induce the resistance against IFN-α therapy and cause poor prognosis, which implied that SOCS1 might be a negative prognostic biomarker in the chronic myeloid leukemia treated with IFN-α." (PMID 28228755, 2017). "In patients with chronic myeloid leukemia (CML), SOCS1 is often hypermethylated, but can revert to the unmethylated state during remission." (PMID 26788993, 2016). "It should also be noted that SOCS1 overexpression has been reported to subvert IFN-α therapy in chronic myeloid leukemia, therefore, a balance, rather than an excess, of SOCS1 is required for normal cell functioning." (PMID 31105556, 2019).
gastric cancer (10 papers, 2004 to 2023). A primary or metastatic malignant neoplasm involving the stomach. "The present study has brought out that H. pylori-mediated epigenetic silencing of SOCS1 in concert with inflammatory cytokines causes hyperactivation of the JAK/STAT cascade during gastric cancer development." (PMID 33569347, 2020). "Methylation of SOCS-1 also correlated with the loss of mRNA expression in some primary gastric cancers." (PMID 15354212, 2004). "The present study has brought out that H. pylori-mediated cytokine signaling promotes gastric cancer development through hypermethylation of SOCS-1 gene promoter and aberrant activation of JAK-STAT cascade." (PMID 33569347, 2020). "Recently, it has been found that hyperactivation of JAK/STAT in H. pylori-infected gastric cancer patients occur via hypermethylation of promoter region of SOCS1 gene." (PMID 33569347, 2020). "It has been reported that hypermethylation of SOCS1 significantly retarded growth and proliferation of variety of gastric cancer cell lines." (PMID 33569347, 2020). "A recent study showed that the SOCS1 antagonist enhanced antigen presentation of human dendritic cells for increased cytotoxic T cell response against human gastric cancer cells." (PMID 26617608, 2015). "This study provides evidence that the activation of JAK/STAT pathway by aberrant SOCS-1 methylation in gastric cancer." (PMID 15354212, 2004). "Concomitant expression of IL-6 and SOCS-1 can be observed in most gastric cancer cell lines, except KATOIII and AGS cell." (PMID 15354212, 2004). "Taken together, these findings suggested that SOCS-1 play an important role in the inhibition of IL-6-mediated STAT3 activation in AGS gastric cancer cell line." (PMID 15354212, 2004). "We investigated the expression level of interleukin-6 (IL-6) and SOCS-1 in gastric cancer cell lines." (PMID 15354212, 2004). "We further showed that downregulation of SOCS-1 correlated with the methylation status in primary gastric cancer." (PMID 15354212, 2004). "Downregulation of SOCS-1 cooperates with IL-6 in the activation of JAK/STAT pathway in gastric cancer." (PMID 15354212, 2004). "In conclusion, this is the first report to demonstrate that hypermethylation of SOCS-1 led to gene silencing in gastric cancer cell line and primary tumour samples." (PMID 15354212, 2004). "In the present study, we found that there was downregulation of SOCS-1 gene in gastric cancer cell line AGS due to gene promoter hypermethylation." (PMID 15354212, 2004). "Since expression of IL-6 upregulates SOCS-1, which participates in the negative regulation of the JAK/STAT pathway, we further analysed the expression of SOCS-1 in these gastric cancer cell lines." (PMID 15354212, 2004). "We found that most of the patients (~86.5%) with H. pylori-infected gastric cancer tissues had hypermethylation of promoter region of SOCS-1 gene which could be a possible reason for the devastating nature of gastric cancer." (PMID 33569347, 2020). "The current study may provide clue to the underlying mechanism that H. pylori-mediated cytokine expression-enhanced tumour progression in a subset of gastric cancer where SOCS-1 was hypermethylated." (PMID 15354212, 2004). "Downregulation of SOCS-1 was also observed in primary gastric cancer with methylation of SOCS-1." (PMID 15354212, 2004). "Numerous studies on DNA methylation report the existence of more than 100 tumor suppressor genes in gastric cancer, including E-cadherin, RASSF1A, p16, GSTP1, SOCS1, SFRP1, and PTEN." (PMID 28512631, 2017). "Also, the low expression of SOCS-1 and SOCS-3 is an indicator of a poor prognosis of gastric cancer, which might be of prognostic significance." (PMID 28512631, 2017).
myeloproliferative neoplasm (10 papers, 2015 to 2023). A clonal hematopoietic stem cell disorder, characterized by proliferation in the bone marrow of one or more of the myeloid (i.e., granulocytic, erythroid, megakaryocytic, and mast cell) lineages. "In summary, we conclude that under pro-proliferative cytokine stimulation at the onset of myeloproliferative diseases SOCS1 acts as a tumor suppressor, while under anti-proliferative conditions it exerts oncogenic function." (PMID 28753604, 2017). "In pro-proliferative cytokine environment—and we assume that particular situation at the onset of myeloproliferative diseases—SOCS1 suppresses the predominantly pro-proliferative cytokines and thus prolongs or even prevents BCR-ABL mediated transformation." (PMID 28753604, 2017). "Previous study has demonstrated that curcumin can effectively induce the expression of SOCS-1 through inhibiting the activity of class I histone deacetylases in myeloproliferative neoplasms." (PMID 27544348, 2016). "Some BCR-ABL-negative myeloproliferative neoplasms (MPN) also exhibit SOCS1 hypermethylation, which may complement other mutations, such as the hyperactive JAK2V617F mutation." (PMID 26788993, 2016). "In hematopoietic progenitors obtained from myeloproliferative neoplasm patients, Curcumin elevated the transcript levels of Socs1 and Socs3 by inhibiting the histone deacetylase activity." (PMID 25822711, 2015). "If however an anti-proliferative cytokine environment is present—which might well be the case at other stages of myeloproliferative disease or other diseases in general—SOCS1 exerts a very different function." (PMID 28753604, 2017). "Furthermore, curcumin can also increase the expression of SOCS-1 through inhibiting class I histone deacetylases in myeloproliferative neoplasms." (PMID 27544348, 2016). "Histone deacetylase inhibitor, that is, sodium butyrate, increases the transcript and protein expression levels of SOCS1 and SOCS3 by triggering the histone acetylation of SOCS1 and SOCS3 gene promoters in myeloproliferative neoplasm." (PMID 28228755, 2017). "As suppressor of cytokine signaling, SOCS-1, is an important negative regulators of JAK/STAT signaling shown in myeloproliferative neoplasms (MPNs) and leukemia." (PMID 27544348, 2016). "In myeloproliferative neoplasm (MPN) cells, HDAC8 suppresses the expression of SOCS1 and SOC3." (PMID 36231123, 2022).
Cirrhosis (9 papers, 2010 to 2025). A chronic disorder of the liver in which liver tissue becomes scarred and is partially replaced by regenerative nodules and fibrotic tissue resulting in loss of liver function. "The studies using SOCS1-deficient mice revealed that endogenous SOCS1 is critical for the prevention of liver diseases such as hepatitis, cirrhosis, and cancers." (PMID 20862390, 2010). "Several studies have indicated that during hepatic chronic diseases and cirrhosis, the expression of SOCS1 decreases and this expression diminishes along with cirrhosis progression." (PMID 32128089, 2019). "In patients with chronic HCV infection, intrahepatic mRNA level of SOCS1 was associated with treatment outcomes following IFN-α therapy and degree of cirrhosis." (PMID 26193702, 2015). "To observe the difference in SOCS1 expression between normal liver tissue and HCC, we verified SOCS1 expression in the Oncomine-Online Platform and found that SOCS1 was downregulated in patients with cirrhosis and HCC and more significantly decreased in those with HCC." (PMID 32096766, 2020). "It has also been shown that SOCS1 gene is silenced by hypermethylation in cirrhosis." (PMID 32128089, 2019). "Furthermore, the expression of SOCS1 as a modulator of hepatic inflammation decreases in cirrhosis condition." (PMID 32128089, 2019). "In addition, public Gene Expression Omnibus (GEO) data analysis showed that TM4SF5 expression was highly elevated in HCC patients, and these elevated levels were negatively correlated with SOCS1 expression in both cirrhosis and HCC patients compared with the normal population." (PMID 34921636, 2021). "Although previous studies have indicated that thalidomide inhibits fibrosis and inflammation progression in cirrhosis, there are not enough studies concerning its role in cirrhotic cardiomyopathy and also the involvement of SOCS1 in this effect." (PMID 32128089, 2019).
diffuse large B-cell lymphoma (9 papers, 2013 to 2025). "For example 35% of primary mediastinal B-cell lymphomas and 16% of diffuse large B-cell lymphomas harbor SOCS1 mutations." (PMID 26336985, 2015). "For example, diffuse large B-cell lymphoma with SOCS1 mutation–which can be identified through NGS–has a better 5-year overall survival after treatment with rituximab, cyclophosphamide, doxorubicin, vincristine, and prednisone as compared to other molecular subtypes." (PMID 40161372, 2025). "Additionally, SOCS1 and SOCS3 epigenetic silencing were occasionally detected, and SOCS1 was frequently mutated in diffuse large B-cell lymphoma and polymorphic posttransplant lymphoproliferative disorders, possibly as a cause of aberrant somatic hypermutation." (PMID 24757565, 2014). "Suppressor of cytokine signaling 1 (SOCS1) is frequently mutated in primary mediastinal and diffuse large B-cell lymphomas (DLBCL)." (PMID 23296022, 2013). "Gene polymorphisms of SOCS1 and its expression have been studied in several malignancies including diffuse large B-cell lymphoma and acute lymphoblastic leukemia, where, particularly, the expression level of SOCS1 was lower compared to the control group." (PMID 38435839, 2024). "Mutations in SOCS1, including those in the SH2 domain, were reported in B‐cell malignancies such as diffuse large B‐cell lymphoma and FL." (PMID 34791836, 2022).
glioblastoma (9 papers, 2015 to 2026). The most malignant astrocytic tumor (WHO grade IV). "PBMCs from glioblastoma patients exhibited increased expression of the regulatory genes SOCS1, SOCS3, and PTEN, while CCND1 was downregulated." (PMID 41898348, 2026). "Interestingly, SOCS1 sensitizes glioblastoma cells to radiation, whereas SOCS3 enhances tumor cell survival and radioresistance." (PMID 25849377, 2015). "Conversely, radioresistant glioblastoma (GBM) highly expresses negative regulators of the IFN–JAK–STAT signaling (SOCS1 and SOCS3) and attenuates IFN–JAK–STAT signaling." (PMID 34830176, 2021). "However, SOCS1 acted like a radiosensitizer in glioblastoma cells." (PMID 25849377, 2015). "As SOCS1 and SOCS3 have been involved in response to radiation in glioblastoma, clonogenic assays were performed to evaluate the possible contribution of SOCS gene expression to radioresponsivity." (PMID 25849377, 2015). "Interestingly, it was found that in glioblastoma (GBM) cell lines, SOCS1 and SOCS3 are regulated reciprocally and SOCS3 is highly expressed in GBM, while SOCS1 is not." (PMID 31632280, 2019). "The expression of SOCS1 and SOCS3 in glioblastoma (GBM) cells is decreased." (PMID 36835292, 2023).